RNU6-498P (RNA, U6 small nuclear 498, pseudogene)
Gene: Small nuclear RNA gene on chromosome 15 (20,738,679 to 20,738,785, forward strand). Ensembl gene ENSG00000238478.
Homologues: Orthologues: macaque U6 (92% identical), rat U6 (84% identical). Paralogues in human: RNU6-1235P (100% identical), U6 (100% identical), RNU6-331P (95% identical), RNU6-25P (91% identical), RNU6-38P (91% identical), RNU6-1 (90% identical), RNU6-2 (90% identical), RNU6-20P (90% identical), RNU6-3P (90% identical), RNU6-41P (90% identical), RNU6-4P (90% identical), RNU6-5P (90% identical), and 1287 more.